TARDBP (TAR DNA binding protein)
Diseases named in the same sentence as TARDBP in open-access papers (continued):
Sharing a sentence is not in itself a finding about the gene and the disease.
neurodegenerative disease (continued). "TAR DNA-Binding Protein 43 (TDP-43) has been well studied in neurodegenerative diseases, but its potential role in malignance is still unclear." (PMID 35963893, 2022). "KPNA3 and KPNA4 were also studied regarding the transport of TAR DNA-binding protein 43 (TDP-43) and the formation of aggregates of this protein in the central nervous system, which is a hallmark of many neurodegenerative diseases." (PMID 35927988, 2022). "From a neuropathological point of view, neurodegenerative diseases are characterized by the deposition of misfolded proteins, such as amyloid beta (Aβ) and tau aggregates for AD and TAR DNA-binding protein 43 (TDP-43) in ALS and FTD." (PMID 36009055, 2022). "Aberrant function of several RNA binding proteins including TAR DNA-binding protein 43 (TDP-43), Fused in Sarcoma (FUS) and Senataxin (SETX) has been linked to neurodegenerative disease pathogenesis." (PMID 35321094, 2022). "TDP-43, encoded by the TAR DNA-binding protein (TARDBP) gene, is the main component of ubiquitinated aggregates present in >95% of all sALS cases, ~50% of FTD cases and numerous other neurodegenerative diseases." (PMID 33925602, 2021). "Defects in these proteolytic systems cause aggregation of amyloid β, tau, α-synuclein, polyglutamine, and TAR DNA-binding protein 43 (TDP-43) in neurodegenerative diseases." (PMID 33685517, 2021). "In the past decade, TDP-43, encoded by the TARDBP gene, was revealed as a key player in the pathogenesis of various neurodegenerative diseases." (PMID 33126923, 2020). "TAR DNA-binding protein 43 (TDP-43) is another δ-secretase substrate involved in neurodegenerative diseases." (PMID 31911834, 2020). "One of the proteins most involved in neurodegenerative diseases is the TAR DNA-binding protein 43 (TDP-43)." (PMID 29617352, 2018). "TDP-43 (TAR DNA binding protein 43) is a heterogeneous nuclear ribonucleoprotein (hnRNP) that has been found to play an important role in neurodegenerative diseases." (PMID 26571498, 2015). "Tar DNA-binding protein-43 (TDP-43) is mostly a nuclear protein under normal conditions, but cytoplasmic accumulation is associated with ALS and other neurodegenerative diseases." (PMID 25643626, 2015). "Recently, Tar DNA-binding protein (TARDBP) gene-encoded product TDP-43 (TDP) was discovered as the major component of the signature inclusion bodies in ALS/FTLD-U, and several other neurodegenerative diseases, collectively called TDP proteinopathy." (PMID 21850253, 2011). "Interestingly, proteins known to be implicated in neurodegenerative diseases other than AD, such as SNCA, pSNCA-129, Oligo-SNCA, SOD1, and TARDBP were also significantly associated with AD." (PMID 40678230, 2025). "TARDBP mutation is a good example, since TAR DNA binding protein-43 (TDP-43) controls non-coding and protein-coding RNA splicing, including relevant proteins of neurodegenerative diseases, and contributes to the survival of neurons as well." (PMID 36983813, 2023). "A recent study showed that the combined measurement of NfL and TAR DNA‐binding protein‐43 (TDP‐43) on CSF had a higher diagnostic accuracy than NfL alone for ALS cases compared to age‐matched controls without neurodegenerative disease." (PMID 35715961, 2022). "SGs are even hypothesized to act as a seeding mechanism for the pathological aggregation of proteins seen in many neurodegenerative diseases, including TAR DNA-binding protein 43 (TDP-43) in ALS." (PMID 33281563, 2020). "Both of these degenerative diseases are characterised by cytoplasmic aggregates containing ubiquitinated and disease-causing mutant proteins within neurons and glia, most frequently the RNA-binding protein TAR-DNA binding protein 43 (TDP-43)." (PMID 29037990, 2017).
neurodegenerative disease (continued). "In the present study we showed that mutations in TARDBP and C9ORF72 genes, associated to defects in RNA metabolism in ALS and FTD neurodegenerative diseases, affect mitochondria functionality by altering several morphological and bioenergetics parameters in a gene-specific manner." (PMID 27151080, 2016). "TDP-43, a multi-functional DNA/ RNA-binding protein encoded by the TARDBP gene, has emerged as a major patho-signature factor of the ubiquitinated intracellular inclusions (UBIs) in the diseased cells of a range of neurodegenerative diseases." (PMID 23721326, 2013). "Here, we report on the extensive mutation screening of TARDBP in a diverse cohort of clinical and pathological confirmed patients with neurodegenerative diseases characterized by TDP-43 pathology, which led to the identification of 3 additional ALS families with TARDBP mutations." (PMID 18802454, 2008). "Comprehending the regulation of the TARDBP locus and identifying all possible players affecting its epigenetic status and subsequent expression levels are key aspects in understanding the mechanisms underlying ALS pathogenesis or predisposition to aging-associated neurodegenerative diseases." (PMID 40017539, 2025). "We identified 2 novel TARDBP missense mutations (p.N345K and p.I383V) and the known p.M337V mutation in 3 out of 92 familial ALS patients (3.3%), while no mutations were identified in 24 sporadic ALS patients or 180 patients with other neurodegenerative diseases." (PMID 18802454, 2008). "Notably, mutations in SG-associated genes—including MAPT, TARDBP (TDP-43), FUS, ATXN2, TIA1, and HNRNPA1—have been shown to disrupt SG dynamics, impair disassembly, and enhance aggregation propensity, thereby contributing to neurodegenerative disease pathogenesis." (PMID 41278186, 2025). "FTLD is similar to other neurodegenerative diseases in that it is also characterized by buildup of protein aggregates, namely TAR DNA-binding protein 43 (TDP-43)." (PMID 35880011, 2022). "Again, in line with other neurodegenerative diseases, ALS pathophysiology also includes protein aggregation, this time of the TAR DNA-binding protein 43 (TDP43) which can occur in sporadic and familial forms of ALS." (PMID 35313950, 2022). "TAR DNA-binding protein 43 (TDP-43) is considered a major component of the pathogenesis of ALS, FTLD, and other neurodegenerative diseases." (PMID 33562649, 2021). "We previously reported that expression of granulin peptides, the cleavage products of the neurodegenerative disease protein progranulin, enhance the accumulation and toxicity of TAR DNA binding protein 43 (TDP-43) in Caenorhabditis elegans (C. elegans)." (PMID 31398187, 2019). "Cytoplasmic inclusions containing tau, transactive response DNA-binding protein (TARDBP), superoxide dismutase (SOD), and synuclein alpha are the pathological hallmarks of neurodegenerative diseases." (PMID 28596290, 2017). "Molecularly, alterations of TAR DNA-binding protein 43 (TDP-43) and glycogen synthase kinase 3 (GSK-3), two major markers of neurodegenerative diseases, are found." (PMID 27631495, 2016). "In particular, TAR-DNA binding protein 43 (TDP-43), a member of the heterogeneous nuclear ribonucleoproteins (hnRNPs) family, has emerged as a new player in the field of neurodegenerative diseases." (PMID 27193329, 2016). "Although the mammalian prion protein PrP lacks this domain, other neurodegenerative disease proteins such as FUS (Fused in Sarcoma) and TDP-43 (TAR DNA-binding protein 43) have been shown to contain Q/N-rich prion-like domains." (PMID 23555277, 2013). "FTLD-U belongs to the subset of neurodegenerative diseases that are characterized histologically by ubiquitin-positive cytoplasmic and intranuclear neuronal inclusions containing the TAR DNA binding protein, TDP-43." (PMID 20946666, 2010).
neurodegenerative disease (continued). "Although its exact role in the pathogenesis of neurodegenerative diseases remains unclear, studies have shown that TMEM106B appears to affect the pathological burden of TAR DNA binding protein-43 (TDP-43) pathology." (PMID 38710967, 2024). "Importantly, each neurodegenerative disease has typical aggregating proteins, such as amyloid β (Aβ) in AD, tau in AD and FTD, α-synuclein in PD, TAR DNA-binding protein 43 (TDP-43) in ALS and FTD, and mutant huntingtin in HD." (PMID 36726375, 2023). "Moreover, mutations in TARDBP are responsible for both familial and sporadic forms of ALS, suggesting that altered mRNA processing by TDP-43 may contribute to cellular pathology and functional impairment in both sporadic and inherited forms of neurodegenerative disease." (PMID 35311646, 2022). "FTD and ALS are rapidly progressing fatal neurodegenerative diseases with similar disease aetiology and common neuropathological inclusions containing the nuclear TAR DNA-binding protein 43 (TDP-43), which is found in more than 90% of ALS and approximately 50% of FTD cases." (PMID 36291062, 2022). "The absence of TARDBP mutations in patients with neurodegenerative diseases other than ALS in our study, confirms the lack of mutations and genetic association of TARDBP in FTLD populations." (PMID 18802454, 2008). "In conclusion, our findings support that TARDBP mutations are a rare cause of ALS, but so far are not found in other neurodegenerative diseases." (PMID 18802454, 2008). "For example, studies on a protein involved in multiple neurodegenerative diseases, Tar DNA‐binding protein 43 (TDP‐43), revealed that moderate expression of Sti1/Hop reduced TDP‐43 toxicity, while high expression or knockout of Sti1/Hop increased TDP‐43 toxicity." (PMID 40259657, 2025). "Similarly, mutations in non-kinase genes such as TARDBP, mHTT, and OPTN may also promote/reduce kinase activity by regulating abnormal protein expression, thereby unbalancing protein homeostasis and promoting the occurrence of neurodegenerative diseases." (PMID 40328798, 2025). "Twenty-four transcripts were downregulated in recurrence among EGFR non-amplified tumours, and among these was TARDBP (padj = 0.034), coding for the neuronal protein TDP-43, involved in the transcriptional response in neurodegenerative disease via widespread RNA binding interactions." (PMID 36765632, 2023). "Tau, TAR DNA-binding protein 43 (TDP-43), amyloid-β and α-synuclein pathology were rated on a scale of 0 (absent)—3 (severe) in the hippocampus and entorhinal cortex (ERC) of 58 individuals with and without neurodegenerative diseases (median age 75.0 years, 60.3% male)." (PMID 34289895, 2021).
neurological diseases (106 papers, 2008 to 2026). "In-depth research on the role of TDP-43 in RNA metabolism and neuronal integrity can open avenues for targeted interventions in neurological diseases associated with TARDBP." (PMID 40234983, 2025). "Hipk also controls the levels of TBPH, the fly ortholog of TAR DNA-binding protein 43 (TDP-43), associated with the pathogenesis of different neurological diseases." (PMID 36935052, 2023). "Therefore, we infer that the TARDBP gene and mutations thereof also play an important role in several neurological diseases." (PMID 37147573, 2023). "TAR DNA-binding protein-43 (TDP-43) is another RBP that has recently been recognized as an important contributor to neurological diseases." (PMID 23060744, 2012). "A growing consensus suggests that ALS and FTD form part of a continuum of neurological diseases that share a common pathological background, consisting of TAR DNA-binding protein 43 (TDP-43)-positive inclusions within the CNS." (PMID 22406228, 2012). "The highest-ranked network in the differentiated SH-SY5Y cells (Score = 51, Focus Molecules = 28) is related to Hereditary Disorders, Neurological Diseases, Organ Injury, and Abnormalities with TAR DNA-binding protein 43 (TARDP), an RNA-binding protein, as the central node." (PMID 38928492, 2024). "The TARDBP mutations identified in our cohort were instead absent in 1,710 Italian healthy controls, including 771 individuals with no reported history of neurological disorders that we previously screened and 939 subjects enrolled in other case-control studies." (PMID 36247987, 2022). "However, the recent discovery of other highly relevant genetic disease-mutations such as TAR DNA binding protein (TDP-43), bring new powerful GEMs models to the researchers in the field to explore the role this gene mutation plays on this complex neurological disorder." (PMID 33297584, 2020). "Mutations and abnormal expression of RNA-binding proteins have been reported to be engaged in different neurological diseases, including FMRP, TAR DNA binding protein 43 (TDP-43), Hu proteins, and FUS." (PMID 34833008, 2021). "Many genes play an important role, with TARDBP, SQSTM1, VCP, FUS, TBK1, CHCHD10, and most importantly, C9orf72 being critical genetic players in these neurological disorders." (PMID 33805659, 2021). "TARDBP, SQSTM1, VCP, FUS, TBK1, CHCHD10, and most importantly C9orf72, are the critical genetic players in these neurological disorders." (PMID 32116499, 2020).
cancer (61 papers, 2012 to 2025). A tumor composed of atypical neoplastic, often pleomorphic cells that invade other tissues. "The relationship between TARDBP expression and tumor mutational burden (TMB) across several cancers highlights its influence on a key hallmark of cancer progression." (PMID 38947395, 2024). "Our study illuminates TARDBP's universal upregulation across various cancers, indicating its involvement in fundamental oncogenic processes and potential impact on genomic instability." (PMID 38947395, 2024). "In diet-induced obese mice, OGT expression and activity were increased relative to lean littermates and corresponded with higher levels of TET1-responsive cancer stem-like cell pathway member TARDBP." (PMID 37231419, 2023). "Nutriment deprivation frequently occurs in solids tumors and its mimics in U87 cells leads to the accumulation of TDP-43 (TAR DNA binding protein), pro-cancer phenotypes and activation of a HDAC6 dependent autophagy at the expense of apoptosis." (PMID 31861179, 2019). "Hence, the link between the level of TARDBP and activity of ubiqutin-proteasome system and autophagosome is another good example underlying importance of these cellular mechanisms in regulation of carcinogenesis or response of cancer cell to anti-cancer treatment." (PMID 23443080, 2012). "MiRNA-520c is an intermediate regulator of TARDBP-mediated regulation of glycolysis in HCC cells and as metabolic changes in metabolism of cancer cells and are often linked with the clinical outcome of patients, the potential role of miRNA-520c is potentially interesting." (PMID 31979312, 2020). "SOX2 has been implicated in growth, tumorigenicity, drug resistance, and metastasis in at least 25 different cancers, TARDBP is involved in apoptosis and cell division, while GFI1B positively regulates c-Myc expression and increases the proliferation rate of cancer cells." (PMID 29950180, 2018). "The finding of increased level of TARDBP in CEM leukemic cells after anti-cancer DNR treatment let us hypothesise that it might significantly contribute to the toxicity toward the tumor cell and positively influence outcome of anti-cancer response." (PMID 23443080, 2012). "Odds ratios were calculated, and the biomarkers that showed significant difference between Non-cancer and CaP were free/total PSA (p = 0.003), TARDBP (p<0.001), TLN1 (p = 0.006) and CALD1 (p<0.001)." (PMID 31404106, 2019). "The study concludes that TARDBP holds significant potential as a novel therapeutic target in HCC and possibly other malignancies, meriting further exploration to integrate TARDBP-targeted therapies into cancer treatment protocols, thereby advancing the field of precision medicine." (PMID 38947395, 2024).
tumor (38 papers, 2012 to 2026). "Additionally, TARDBP's interaction with immune and inflammatory factors within the tumor microenvironment, including its association with immune-stimulatory factors and inverse relationship with immune inhibitors, suggests its role in modulating immune evasion." (PMID 38947395, 2024). "TAR‐DNA‐binding protein‐43 (TDP‐43) is an RNA/DNA binding protein with elevated expression in several neoplasms." (PMID 39023169, 2024). "TARDBP is an RNA-binding protein involved in the cell cycle of HCC tumor cells, and its expression level is related to an advanced stage and high grade of HCC." (PMID 36451087, 2022). "High TARDBP expression was related to high grade of differentiation and more possibilities of tumor thrombus in CPTAC." (PMID 34133325, 2021). "Moreover, recent studies identified that TARDBP would be a novel NRG in the tumour microenvironment." (PMID 39031474, 2024). "FASLG, TNFRSF1B, GATA3, TARDBP, ZBP1, TNFRSF21, and TLR3 are mainly expressed in multiple immune cell types, and immune cells have a role in TME to inhibit tumor progression." (PMID 35899194, 2022). "In addition, we identified mutations in the C-terminal region of TAR DNA binding protein (TARDBP; also known as TDP-43) in relapsed tumor biopsies in JFCR-119 and JFCR-151." (PMID 30872362, 2019). "We previously reported significant elevation of pathway genes TET1, TARDBP, and SRSF2 in TNBC tumor samples obtained from obese (BMI > 30) compared to non-obese (BMI < 30) patients, as measured by qRT-PCR." (PMID 37231419, 2023).
myopathies (30 papers, 2012 to 2025). "TAR DNA binding protein 43 (TDP-43) and p62 are two proteins aggregated in sIBM and have been suggested as potential biomarkers differentiating sIBM over other related inflammatory myopathies." (PMID 37731843, 2023). "Whether TDP-43 aggregation plays a primary role in rimmed vacuole myopathies or is a phenomenon secondary to muscle degeneration is unknown, since genetic evidence linking pathogenic TARDBP variants to skeletal muscle disorders has previously been lacking." (PMID 37000196, 2023).
brain diseases (9 papers, 2012 to 2025). "The TARDBP gene and its expression product TDP43 play an important role in a variety of brain diseases, including ASL and FTD." (PMID 37147573, 2023).
TARDBP also shares sentences with these, for which no sentence is quoted: corticobasal degeneration (35 papers); infection (34); Pick disease (28); hippocampal atrophy (25); prion disease (23); multiple system atrophy (21); atherosclerosis (17); arteriolosclerosis (16); glioblastoma (15); retinal degeneration (14); Anxiety (10); multiple sclerosis (10); epilepsy (9); melanoma (9); neuromuscular disease (9); spinocerebellar ataxia type 2 (9); trauma (9); memory impairment (8); oculopharyngeal muscular dystrophy (8); psychosis (8); ischemia (7); vascular dementia (7); behavioral variant frontotemporal dementia (6); diabetes (6); glaucoma (6); movement disorder (6); non-small cell lung carcinoma (6); Primary lateral sclerosis (6); Aphasia (5); COVID-19 (5).
A further 206 diseases each share a sentence with TARDBP in 5 papers or fewer.